IL33 (interleukin 33)
Diseases named in the same sentence as IL33 in open-access papers (continued):
Sharing a sentence is not in itself a finding about the gene and the disease.
viral infection (continued). "Indeed, viral infections may exacerbate Th2‐high inflammation by inducing epithelial cell‐derived cytokines such as IL‐25, IL‐33, and thymic stromal lymphopoietin (TSLP), which further activate and recruit type 2 helper T cells and eosinophils." (PMID 39466641, 2025). "Hence, the manipulation of alarmin signals such as IL-33 may offer opportunities for improved therapies of recurrent viral diseases." (PMID 31447845, 2019). "Besides, increased IL-33 in pathological settings including tumor immunotherapy, viral infection and graft-vs.-host diseases, suggest that IL-33 overexpression might elicit potent antitumor immunity." (PMID 30619376, 2018). "Therefore, our results describe a previously unknown link between IL-33 expression and Treg cell function in the context of a viral infection." (PMID 28448566, 2017). "The IL-33/ST2 axis expands and activates NK cells and DCs to promote host defenses against viral infection in mice." (PMID 36291105, 2022). "IL-33 is depleted in the SLO by d3 after LCMV infection, yet FRC frequency is not altered, suggesting that prestored nuclear IL-33 is released during viral infections." (PMID 35503257, 2022). "can be translated to other viral infections, for example, vaccinia virus and MHV‐68 infections known to be controlled by IL‐33, remains to be determined." (PMID 33222176, 2021). "Viral infection disrupts the epithelial barrier, resulting in the thymic stromal lymphopoietin and pro-TH2 cytokines IL-25 and IL-33." (PMID 34831860, 2021). "IL-33 and sST2 mRNA levels correlated with IRF1, an IFN induced factor relevant in responses to viral infections and interferon mediated proinflammatory responses highly represented in duodenal tissues in ACD." (PMID 33133101, 2020). "During a systemic infection with lymphocytic choriomeningitis virus, IL-33 promotes the expansion of viral-specific CD8+ T-cells, thus leading to an enhanced protection against viral infection." (PMID 31509992, 2019). "In the process of virus infection and lung damage, the NLRP3 inflammasome pathway is very critical and is closely bound up with IL-1β, IL-33, and IL-18." (PMID 32047436, 2019). "We demonstrated that oxidative stress is involved in the expression of IL-33 in airway epithelial cells via the MAPK signal pathway and that it augments IL-33 expression during viral infection." (PMID 29587772, 2018). "Further, we show that conditioned media from bronchial epithelial cells as well as RV infection and stimulation with viral infection mimics acting on TLR3 and RIG-I-like receptors increase IL-33 in BSMCs from both healthy and asthmatic individuals." (PMID 26318341, 2015). "The transcript level of IL-33 was highly increased in L2-MHV3 induced hepatitis than Poly(I:C) treated mice demonstrating a difference between TLR-3 agonist and natural virus infection in liver." (PMID 24058536, 2013). "Importantly, RV-induced disease was attenuated by anti-IL-33 treatment and in TSLPR knockout mice, suggesting a complex interplay among IL-25, IL-33, and TSLP during viral infections in the lung." (PMID 41409758, 2025). "IL-33/ST2 signaling in effector cells is an essential regulator of immune responses against helminth, fungal, bacterial, or viral infections, either by directly participating in the immune response against the infectious trigger or by driving repair mechanisms after clearance of the infection." (PMID 40384929, 2025). "In animal experiments, IL-33 released by viral infections or cigarette smoking activated NK cells and macrophages, not ILC2, to induce IFN production, which contributed to emphysema development." (PMID 39439801, 2024). "Additionally, the MAPK signaling pathway is involved in regulating IL-33 expression in airway epithelial cells of COPD patients, particularly during viral infections that worsen the condition." (PMID 39301028, 2024).
viral infection (continued). "IL-33, TSLP, and IL-25 are released by the epithelium to promote type 2 immunity, which can inhibit type 1 responses that are important in the defense against viral infections." (PMID 37631998, 2023). "Viruses can induce epithelial disruption, and studies in mice have demonstrated that viral infections can promote the secretion of alarmin cytokines such as IL-33 by non-hematopoietic cells and necrotic cells." (PMID 36311787, 2022). "In the newborn brain with Zika virus-induced microcephaly, IL-33 is significantly upregulated compared to that in newborn brains with microcephaly without virus infection." (PMID 34079543, 2021). "On the other hand, IL-25, IL-33, and thymic stromal lymphopoietin (TSLP), which are mainly secreted from the airway epithelium due to Alternaria, protease activity of antigens such as HDM, and fungus and viral infection, are also involved in type 2 immunity." (PMID 32397396, 2020). "The other studies have concluded that exogenous IL-33, but not endogenous IL-33, is involved in viral infection." (PMID 32210964, 2020). "Collectively, these data indicated that in a host with impaired with antiviral immunity (i.e. IRF7-/- mice), IL-33 and HMGB1 contribute to increased ILC2 numbers, type-2 cytokine production and the development of ASM remodelling in response to an early-life viral infection." (PMID 32658914, 2020). "Finally, exogenous IL-33 enhanced CTL response against influenza infection, which resulted in an increase in IFN-γ production and the PR8 specificity of CD8+ T-cells post-viral infection." (PMID 31509992, 2019). "The IL-33 and TSLP pathways, may be a point of intersection where viral infections and allergic exposures combine to result in increased eosinophilic inflammation and a heightened risk of exacerbation from the activation of eosinophils." (PMID 31490928, 2019). "Viral infections can trigger the release of the alarmin interleukin-33 (IL-33) from non-hematopoietic cells." (PMID 31447845, 2019). "The levels of IL-1β and IL-33, cytokines with important roles in metabolic homeostasis, viral infection, inflammation and carcinogenesis, are not statistically significant different in the two groups, as well as the levels of the immunoregulatory IL-10 and immunostimulatory IFN-γ." (PMID 38961336, 2024). "During bacterial and viral infections, local sensor cells in respiratory tract, including airway epithelia cells, alveolar macrophages and dendritic cells, firstly response to pathogens and secret the first-order cytokines, such as type I and III IFN, IL-6, TNF-α, IL-12, IL-25, IL-33, IL-1β, etc.." (PMID 38029253, 2023). "IL-33, a member of the IL-1 family, is an alarmin cytokine with crucial roles in tissue homeostasis and repair, type 2 immunity, allergic and non-allergic inflammation, viral infection, and cancer." (PMID 37759873, 2023). "Early research showed that IL-33 is required for cytotoxic CD8+ T-cell responses and antiviral immune responses to viral infection in mice lacking IL-33 or its receptor and that IL-33 is irreplaceable for CD8+ T-cell expansion, production of multiple cytokines, and acquisition of cytotoxic function." (PMID 36362440, 2022). "The correlation between serum viral loads and IL-33 is not clear in different viral infections." (PMID 35056005, 2022). "IL-33-dependent ILC2 activation has also been reported during cancer, viral infections, and murine models of autoimmune diseases; and given the observed induction of c-Rel expression in ILC2s from different tissues, modulation of c-Rel function in these conditions may be worth evaluating." (PMID 34867937, 2021). "Although, viral infections such as influenza can induce IL-33 release in murine lungs, it is not clear whether IL-33 can modify cellular responses directed against respiratory viruses." (PMID 30174671, 2018).
viral infection (continued). "Finally, other immunoregulatory cytokines like IL-10 and IL-33 that play important roles in the control of viral infections are highly expressed by MΦs but not by other myeloid subsets, particularly after WNV infection." (PMID 29408905, 2018). "The survival curve analysis revealed that the L2-MHV3-infected IL-33 KO mice started dying earlier between 3 and 6 days PI than the WT mice (median survival 4.5 versus 5 days) but in a nonsignificant manner on the 7 days of viral infection." (PMID 28607531, 2017). "LPS, or maybe farm dust, attenuates the induction of proallergic cytokines, including TSLP, IL33, and others in respiratory epithelial cells in response to viral infection, and it does not disturb the Th1-prone effect of viruses on DCs." (PMID 29065558, 2017). "In the human epithelium IL33 is induced mainly by polyI:C and flagellin, the ligands to TLR3 and TLR5, respectively, following parasitic or viral infections, but also by other non-TLR factors, such as exposure to allergens." (PMID 29065558, 2017). "After a baby is exposed to more environmental LPS, which is relatively nonpathogenic, then when it later encounters a common viral infection, the dsRNA cannot activate the epithelial cells to produce allergic cytokines, such as TSLP, IL33 and IL25." (PMID 29065558, 2017). "In conclusion, the absence of endogenous IL-33 significantly affected the liver infiltration of B lymphocytes, T lymphocytes, NK cells, NKT cells, DCs, and macrophages at early onset of L2-MHV3 viral infection (48 h PI) with a recolonization phenomenon at 72 h PI (except for macrophages)." (PMID 28607531, 2017).
breast cancer (106 papers, 2011 to 2026). A primary or metastatic malignant neoplasm involving the breast. "Both Th-17 and IL-33 have been implicated in carcinogenesis, and elevated plasma levels of these interleukins have been observed in breast cancer as well." (PMID 40669200, 2025). "Proinflammatory signaling from CAFs (IL-33) has also been implicated in establishing a metastatic niche in the context of breast cancer–associated lung metastasis and chemoresistance." (PMID 39007269, 2024). "The IL-33/ST2 axis has been implicated in the progression of breast cancer through the induction of tumor tissue inflammation." (PMID 37762328, 2023). "When it comes to human breast carcinoma, it has been shown that augmented IL-33 expression is associated with endocrine resistance, posing a challenge for some first-line therapeutic modalities." (PMID 37762328, 2023). "In the TCGA dataset, C11orf1, OLA1, RPL31, SPDL1 and IL33 were identified to be associated with prognosis of breast cancer." (PMID 35761863, 2022). "High levels of IL-33 expression occur in gastric cancer, liver cancer, colorectal cancer, lung cancer, breast cancer, and are associated with poor outcome." (PMID 35677533, 2022). "IL-33 was shown to be upregulated in metastases-associated fibroblasts in mouse models of spontaneous breast cancer metastasis and in breast cancer patients with lung metastasis." (PMID 36291105, 2022). "In particular, the implication of IL-33 acting as a “danger” signal in tumor-associated inflammation has been reported in multiple cancers, including breast cancer, gastric cancer, head and neck cancer, lung cancer, and hepatocellular carcinoma." (PMID 34209038, 2021). "A more recent study further reported the potent inhibition of pulmonary metastasis of murine breast cancer by IL-33 administration, which was associated with the elevation of recruited NK cells to the TME." (PMID 34209038, 2021). "In another study, serum levels and genetic polymorphisms of IL-12 and IL-33 were compared among breast cancer patients and healthy cohorts." (PMID 30205617, 2018). "The aim of the present study was to explore the association of serum IL-33 and sST2 with breast cancer." (PMID 26456994, 2015). "Moreover, multiple cohort and experimental studies have shown that elevated IL-33 expression is associated with poor prognosis in breast cancer." (PMID 41284319, 2025). "IL-33 and sST2 are both associated with the development and metastasis of breast cancer." (PMID 38585634, 2024). "IL-33 has been linked to the resistance of melanoma and breast cancer cells to conventional pharmacotherapeutics, which might indicate the possibility of targeting the IL-33/ST2 axis as an immune antitumor adjuvant." (PMID 37762328, 2023). "The expression of IL-33 was increased in metastases-associated fibroblasts, which remodeled the immune microenvironment into a more hospitable inflammatory niche for lung metastasis of breast cancer." (PMID 37495592, 2023). "Serum IL-33 levels have been found to be higher in patients with IGM compared to those with breast cancer, suggesting IL-33 and sST2 could serve as potential differential diagnostic markers in conjunction with radiological and pathological examinations." (PMID 37762328, 2023). "The presence of mast cell is associated with improved prognosis in colorectal and breast cancers; however, mast cells have also been linked to tumor promotion via induction of resistance to anti-PD-1 therapy in melanoma and IL-33-elicited macrophage mobilization in murine models of gastric cancer." (PMID 37064719, 2023). "In breast cancer cells isolated from patients, IL-33 levels could be linked to future tamoxifen resistance." (PMID 37762328, 2023). "IL-33 secreted by cancer-associated fibroblasts is able to recruit inflammatory cells into the metastatic microenvironment, which facilitates the lung metastasis of breast cancer." (PMID 35634336, 2022).
breast cancer (continued). "As IL-1 and IL-33 both use IL-1R3 (IL-1RAcP), it may be speculated that anti-IL-1R3 antibodies may reduce angiogenesis and increase tumor necrosis in breast cancer due to loss of vascular supply." (PMID 26919112, 2016). "Furthermore, there were fewer MDSCs in tumor lesions of Il1rl1-deficient mice, while treatment with exogenous IL-33 promoted the accumulation of these suppressor cells in mammary tumors." (PMID 28119694, 2016). "Understanding of the association of IL-33 and angiogenesis or invasion might help in the design of efficient and safe therapy for breast cancer." (PMID 26456994, 2015). "In the present study, we hypothesized that IL-33 was associated with invasion and angiogenesis of breast cancer and investigated whether serum IL-33 or sST2 was correlated with VEGF, PDGF-C, or MMP-11." (PMID 26456994, 2015). "In addition, radiotherapy for 6 months was found to upregulate IL-33 and sST2 levels, suggesting that radiotherapy for 6 months in breast cancer patients may cause myocardial damage." (PMID 38585634, 2024). "IL-33 strongly activates MCs, which release mediators that promote the growth, vascularization, and progression of breast cancer." (PMID 41596472, 2026). "Enhanced IL-33/Wnt signalling facilitates the metastatic potential of the breast cancer, while genetic or pharmacological silencing of this axis inhibits tumour spread." (PMID 41284319, 2025). "In mouse models of breast cancer (4T1 model), IL-33 increased the number of ILC2s, M-MDSCs, and Tregs." (PMID 40497988, 2025). "In mouse model of breast cancer, simultaneous blockade of both the IL-33/ST2 and PD-1/PD-L1 signalling pathways significantly delayed palpable tumour appearance (ST2–/– + antiPD1 vs. WT= 15th vs. 10th day) and slowed tumour growth." (PMID 41284319, 2025). "Recent studies have indicated that IL33, which is secreted by fibroblasts, promotes the establishment of a proinflammatory microenvironment conducive to breast cancer metastasis to the lungs, a process characterized by a type II inflammatory response." (PMID 40082673, 2025). "Dissecting out the roles of the PD-1/PD-L1 and IL-33/ST2 signalling pathways in breast cancer biology has significant clinical outcome." (PMID 41284319, 2025). "Another study revealed that IL-33 levels and the IL-33/IL-12 ratio were significantly higher in stage IV breast cancer patients than other stages and controls (p < 0.0001 and p < 0.001, respectively)." (PMID 41284319, 2025). "Current literature on the PD-1/PD-L1 and IL-33/ST2 pathways in breast cancer progression was synthesized, focusing on their mechanisms of immune suppression and TME modulation." (PMID 41284319, 2025). "The prognostic significance of IL-33/ST2 signalling activity in breast cancer remains an active area of investigation." (PMID 41284319, 2025). "Our previous study indicated a positive correlation between advanced stage of breast cancer and increased expression of IL-33." (PMID 41284319, 2025). "IL-33 is a cytokine found in both mouse and human colorectal and breast cancers, which can activate ILC2s." (PMID 40497988, 2025). "By using a 4T1 mouse model of breast cancer, we showed that IL-33 administration led to accelerated tumour growth and accelerated metastasis into lung and liver." (PMID 41284319, 2025). "In the metastatic microenvironment, the upregulation of fibroblast-derived IL33 expression triggers type 2 inflammation; mediates the recruitment of eosinophils, neutrophils and inflammatory monocytes to the lung; and promotes breast cancer metastasis." (PMID 41214328, 2025). "The IL‐33/ST2L axis promotes tumor progression in a mouse model of breast cancer by suppressing innate antitumor immunity through the accumulation of immunosuppressive cells." (PMID 40751595, 2025). "The IL-33/ST2 signalling axis has attracted increasing interest in breast cancer research due to its diverse and sometimes contradictory effects on tumour progression and immunoregulation." (PMID 41284319, 2025).